FGF2 (fibroblast growth factor 2)
Diseases named in the same sentence as FGF2 in open-access papers (continued):
Sharing a sentence is not in itself a finding about the gene and the disease.
tumor (1,857 papers, 1992 to 2026). "Increased CAF abundance and overexpression of growth factors such as platelet-derived growth factor (PDGF), TGF-β, and fibroblast growth factor 2 (FGF2) are closely associated with tumor angiogenesis and ECM remodeling." (PMID 40574854, 2025). "Earlier studies have shown that within the tumor microenvironment, lmw-FGF2 promotes the M2-phenotype of tumor-associated macrophages and the exhaustion of CD8 + T-cells." (PMID 40425576, 2025). "FGF2 is overexpressed in EC tissues and is also associated with tumor size, gender, and lymph metastasis in patients with EC." (PMID 41141624, 2025). "In order to overcome this barrier, the tumor cells are able to produce fibroblast growth factor 2 (FGF2), which increases the susceptibility of CAFs to infection with OVs, promoting better targeting of CAFs and disruption of the ECM." (PMID 40612869, 2025). "For example, tumor-derived FGF2 enhances the survival and migration of tumor-associated macrophages (TAMs) and skews them toward an immunosuppressive phenotype, thereby establishing a microenvironment conducive to angiogenesis and tumor progression." (PMID 41514604, 2025). "Fibroblast growth factor 2 protein encoded by the FGF2 gene involves various biological processes like tissue repair, embryonic development, tumor growth, and cell survival." (PMID 38626166, 2024). "CLL cells and tumor-associated stromal cells also produce and secrete FGF-2, TNF-α, CXCL-12, CXCL-2, NGAL, IGF-1, progranulin, and angiogenin." (PMID 39796700, 2024). "In solid tumors, MMP-9 can release VEGF and FGF-2 sequestered in the extracellular matrix, which in turn activate tumor-associated ECs." (PMID 39796700, 2024). "Tumor-associated macrophages express high levels of FGF2, influencing their behavior and interactions within the tumor microenvironment." (PMID 38745238, 2024). "In HNSCC, it has been shown that tumor cells, through the secretion of FGF2, promote the activation of the FGF2/FGFR2 axis in cancer-associated fibroblasts (CAFs) in the dermis." (PMID 38248804, 2024). "Recent research has shown that IGFBP7 promotes the polarization of tumour‐associated macrophages (TAMs) via the FGF2/FGFR1/PI3K/AKT axis, thereby facilitating the progression of GC." (PMID 39351597, 2024). "Their findings demonstrated that CAFs facilitate tumor growth by secreting FGF2 and promoting the conversion of tumor-associated macrophages (TAMs) into the M2 phenotype, which supports tumor progression." (PMID 38491511, 2024). "FGF2 produced by tumor-associated fibroblasts reportedly contributes to maintenance of tumor cell immaturity and aggressiveness." (PMID 38062130, 2023). "To uncover how FGF2 promotes tumor associated macrophage infiltration, we compared the transcriptome of M0, M1, and M2 macrophages using GSE159112 datasets." (PMID 36681667, 2023). "Exogenous recombinant IGFBP7 treatment in macrophages and GC cells further identified that IGFBP7 promotes tumor associated macrophage (TAM) polarization via FGF2/FGFR1/PI3K/AKT axis." (PMID 36681667, 2023). "Another critical marker of induced angiogenesis, α5β1 integrin, is associated with tumor malignancy, invasiveness, and metastasis formation in response to various stimuli, such as FGF2." (PMID 37569595, 2023). "FGF2 is interestingly associated with resistance to antiangiogenic therapy, poor survival, and increased tumor fibrosis, which can impede intratumoral drug accumulation." (PMID 36338570, 2022). "It is well documented that FGFs, in particular FGF1 and FGF2, promote tumor-associated angiogenesis and induce the formation of new vessels that provide oxygen and nutrients, and that facilitate cancer cell dissemination." (PMID 35409195, 2022). "It was further demonstrated that FGF2‐dependent angiogenesis, tumour growth and metastasis were enhanced in Ptx3‐deficient mice." (PMID 35090088, 2022). "PRSS23 functions as an oncogene in GC by enhancing tumor associated macrophage infiltration via FGF2." (PMID 36189305, 2022).
tumor (continued). "We next investigated the underlying mechanism by which the tumor cell–derived FGFBP1-triggered activation of the FGF2/FGFR1 axis induced FAPα expression in HSCs." (PMID 35951441, 2022). "Clinically, high levels of FGF2 were detected in mixed/epithelioid specimens, associated with a poor prognosis, compared to spindle cell type tumor samples." (PMID 35409195, 2022). "In this work, we took a cross-platform approach to identify that FGF-2 is highly expressed in clinical NPC samples, and we developed various mouse models to study the molecular mechanisms underlying FGF-2–promoted tumor metastasis." (PMID 35439170, 2022). "The results showed that both PRSS23 and FGF2 were significantly overexpressed in M2 macrophage, which is highly similar to tumor associated macrophage." (PMID 36189305, 2022). "Mechanismly, PRSS23 promotes tumor associated macrophage infiltration by regulating FGF2 expression and secretion." (PMID 36189305, 2022). "VEGF and FGF2 stimulate the migration and proliferation of tumor-associated endothelial cells, leading to tumor angiogenesis and stability in RCC." (PMID 33746989, 2021). "FGF-2’s mode of action is not limited to cell proliferation, but has also been indirectly linked to tumor angiogenesis." (PMID 34638361, 2021). "It has also been reported that fibroblast growth factor 2 (FGF-2) suppresses the action of TGF-β on cancer-associated fibroblasts (CAFs) to promote tumor formation." (PMID 34298705, 2021). "UALCAN analysis has shown an upregulation of FGF2 in normal tissues, in comparison to primary BC and FGF2 downregulation is associated with tumor progression." (PMID 32050925, 2020). "Blocking FGF2 with a specific antibody led to diminished tumour regrowth after irradiation that was associated with an increase in M1 polarisation of TAMs." (PMID 32792542, 2020). "It is well established that FGF2/FGFR signaling deregulation is associated with aggressive tumor phenotypes and drug resistance, features recurrently linked to the poorly differentiated HCC subtypes." (PMID 32517019, 2020). "In a study of MCaIV syngeneic tumor models, cancer-associated fibroblasts and adipocytes expressed FGF2 and mediated resistance to anti-mouse VEGF Ab B2013." (PMID 32076044, 2020). "Tumours in mice genetically deficient in low-molecular weight FGF2 (FGF2LMW) regress dependent on T cells." (PMID 32792542, 2020). "There are nocomparable studies of FGF-2 on macrophages in other systems, however it has beenshown that it increases the migration and survival of tumor-associated macrophages." (PMID 31048836, 2019). "FGF2 is a proangiogenic factor implicated in tumor angiogenesis and already proved to induce proliferation, migration and tube formation in HUVEC." (PMID 29566097, 2018). "LncRNA-MALAT1 promoted FGF2 protein secretion in tumor-associated macrophage, leading to inhibited inflammatory cytokine release, and thus promoting the proliferation and metastasis of thyroid cancer." (PMID 29752439, 2018). "In this experimental model, PTX3-expressing TEMs were able to efficiently deliver the PTX3 protein to the tumor site in a syngeneic FGF2-dependent model of prostate cancer, causing a significant reduction of the growth of the tumor grafts." (PMID 30349543, 2018). "FGF2 encodes fibroblast growth factor 2, a protein with mitogenic and angiogenic activities, which contributes to tumor growth." (PMID 28629469, 2017). "FGF2 is a growth factor implicated in various biological processes such as wound healing, tumour growth, and angiogenesis." (PMID 29186820, 2017). "FGF-2 expression was significantly associated with sex (p<0.013) and tumor differentiation (p<0.0001) in OSCC patients." (PMID 26465941, 2015). "Experimental evidence correlates tumor vascularization with high malignancy and poor prognosis, and shows that elevated levels of angiogenic factors, such as VEGF and basic Fibroblast Growth Factor (FGF-2), are associated with tumor progression." (PMID 18447899, 2008).
tumor (continued). "The proteoglycans in the cancer pathway also show significant involvement, with 10 genes and an FDR of 1.75 × 10−6, encompassing genes such as MMP2, FGF2, and PKAc, which are associated with extracellular matrix remodelling and tumour microenvironment regulation." (PMID 40699738, 2025). "A recent study demonstrated that FGF-2 is involved in shifting tumor-associated macrophages (TAMs) toward the M2-phenotype (pro-tumorigenic) in the tumor microenvironment, as evidenced by comparisons between wild-type mice and mice genetically deficient in FGF." (PMID 38672507, 2024). "Inhibiting FGF2 reversed the tumor-promoting effects caused by METTL3 downregulation in LUAD cells." (PMID 39497721, 2024). "Single-cell analysis and gene expression correlation analysis showed that PRSS23 and FGF2 were high expressed in fibroblasts, and highly co-expressed with the biomarkers of tumor associated macrophages (TAMs), cancer-associated fibroblasts (CAFs) and mesenchymal cells." (PMID 36189305, 2022). "Furthermore, our data showed that the circ_0018289/miR-183-5p/TMED5 axis contributed to an elevated expression of VEGFA and FGF2, two angiogenesis inducers, leading to induction of tumor-associated angiogenesis." (PMID 34404391, 2021). "FGF2 is a known angiogenesis-associated molecule implicated in tumor progression." (PMID 33446839, 2021). "Some tumor cell associated cytokines such as cytokines and angiogenic factors (CAFs)which can support the proliferation of tumor cell.FGF-2, HGF, VEGF, and PDGF-β plasma levels at diagnosis are indicative of more profound response since lower angiogenesis to MM cell." (PMID 34290698, 2021). "We speculate that the FGF2 variant investigated here could influence the expression of specific isoforms, which might then uniquely influence tumour progression in response to BVZ." (PMID 33573134, 2021). "Even though further studies are awaited to elucidate the details, the tumor microenvironment rich in VEGF-A and FGF-2 may partly account for the upregulation of LAT1 in tumor-associated endothelium." (PMID 33256804, 2020). "Similarly, a long non-coding RNA (lncRNA), MALAT1, was found to promote angiogenesis in thyroid cancer tissues by increasing FGF2 secretion from tumor-associated macrophages." (PMID 32993787, 2020). "Many molecules and cell types participate in the process of tumor angiogenesis, such as vascular endothelial growth factor (VEGF), fibroblast growth factor-2 (FGF-2), matrix metalloproteinases (MMPs), tumor-associated macrophages (TAMs), and tumor-associated fibroblasts (TAFs)." (PMID 32169087, 2020). "In addition, a previous study showed that significant upregulation of JMJD2B in tumor tissues promoted the expression of fibroblast growth factor 2 and became a risk factor for the development of OS." (PMID 32802732, 2020). "In CRC, a MAX/MYC heterodimer induced by elevated HIF-2α mediates transcriptional repression of hypoxia-related miR-15-16, leading to tumor angiogenesis and hematogenous metastasis by further loss of post-transcriptional restriction towards fibroblast growth factor-2." (PMID 32102656, 2020). "Accordingly, we examined the effect of FGF2 on the irradiation response, and found that a blocking antibody to FGF2 in combination with radiotherapy reduced or even eliminated tumour regrowth in association with an increase in the TAM iNOS+/CD206+ ratio (also called a M1/M2 ratio)." (PMID 32792542, 2020). "Hence, pharmacological inhibition of MAGL was able to reduce tumor volume, which was further associated with downregulation of fibroblast growth factor-2 (FGF-2) and vascular endothelial growth factor (VEGF)." (PMID 31060243, 2019). "To evaluate whether the inhibition of lung SCC tumor xenograft growth by honokiol was associated with the downregulation of FGF2, we determined the levels of FGF2 in the mRNA extracted from tumor samples by RT‐PCR." (PMID 30515999, 2018).
tumor (continued). "In addition, increased circulating platelets and neutrophils produce vascular endothelial growth factor, angiopoietin-1, and fibroblast growth factor-2, causing tumor angiogenesis." (PMID 29029493, 2017). "Thus, the difference in sensitivity to FGF2 between KO/PyMT and WT/PyMT tumour cells, caused by α3(V) ablation, is GPC1-dependent." (PMID 28102194, 2017). "Moreover, immunoprecipitations from tumour extracts and analysis of FGF2 amounts associated with the ECM of WT/PyMT, KO/PyMT, and GPC1 knockdown tumour cells supported the conclusion that the three proteins interact in vivo." (PMID 28102194, 2017). "FGF2 is a growth factor strongly implicated in tumor cell growth." (PMID 27590504, 2016). "IL-1β can facilitate tumor-associated inflammation, rendering the tumor stroma carcinogenic via the release of trophic factors such as FGF2 and VEGF which allow malignant cells, cancer-associated fibroblasts (CAFs) and endothelial cells to fuel and foster tumor cell survival and invasiveness." (PMID 27528423, 2016). "The binding properties of CSE for a large variety of tumour associated growth factors such as FGF2 and VEGF, but also important adhesion molecules including N-cadherin and E-cadherin may be instrumental in this regard." (PMID 25372710, 2014). "Basic fibroblast growth factor (FGF2, encoded on the “sense” DNA strand), is a pleiotropic factor implicated in a multitude of physiologic and pathologic processes, including angiogenesis, wound healing, and tumor growth." (PMID 24704982, 2012). "FGF-2 has been the first tumor-associated angiogenic factor to be purified." (PMID 21317461, 2010). "Furthermore, Fuster and colleagues demonstrated that interfering with the interaction between heparan sulfate and VEGFA/FGF-2 may potentially represent a good strategy to target tumor-associated ECs, at least in lung cancer model." (PMID 32456248, 2020). "Endovascular injection of adeno-associated virus harboring the PTX3 cDNA was used to block FGF2-mediated intimal thickening after balloon injury in the rat carotid artery whereas its retroviral/lentiviral transduction has been exploited to inhibit FGF activity in different tumor models." (PMID 30349543, 2018). "Moreover, when considering the role of FGF2 in the formation and maintenance of lymphatic vessels, it is possible to hypothesize that PTX3 may inhibit FGF2-mediated lymphangiogenesis and its associated events, including tumor metastatic dissemination." (PMID 30349543, 2018). "Dysregulation of the hypothalamic–pituitary–adrenal axis can facilitate tumor progression through the upregulation of signaling molecules such as fibroblast growth factor 2 and activation of epithelial–mesenchymal transition pathway." (PMID 41409248, 2025). "In cancer, FGF2 promotes tumor angiogenesis and cell proliferation, while under oxidative stress conditions, it enhances the cellular antioxidant defense by upregulating the expression of antioxidant enzymes (SOD, CAT, and GSH-Px) and maintaining GSH levels." (PMID 40363725, 2025). "In colorectal and other solid tumor models, stromal cell-derived or membrane-bound FGFs (such as FGF2) activate downstream FGFR signaling to promote tumor cell migration, invasion, and stem-like phenotypes." (PMID 41514604, 2025). "GABA also promotes tumor neovascularization by increasing the expression of fibroblast growth factor 2 (FGF2) in macrophages." (PMID 41415714, 2025). "Elevating IGFBP7 level promotes tumor progression by enhancing TAM/M2 macrophage polarization through the FGF2/FGFR1/PI3K/AKT axis in GC59,60." (PMID 40032943, 2025). "In various cancers, including breast, lung, and prostate, FGF2 has been shown to promote tumor growth and angiogenesis." (PMID 39833941, 2025). "Instead, the soft matrix caused these alterations via epithelial tumor cells through triggering upregulation of the cyclooxygenase 2 (COX2) pathway activity and secretion of fibroblast growth factor 2 (FGF2), leading to subsequent immune suppression." (PMID 40425576, 2025).
tumor (continued). "FGFR2+ functional CAFs, which have differentiated in ESCC, can be mobilized by tumor-secreted FGF2 and recruited to the tumor site through the CXCL12–CXCR4 axis." (PMID 40134607, 2025). "CAF release pro-angiogenic factors such as VEGFA, PDGFC, and FGF2 to stimulate or adversely affect angiogenesis in tumor tissues." (PMID 40485724, 2025). "NEP is known to degrade several biologically active peptides such as fibroblast growth factor-2 and insulin-like growth factors that play an important role in tumour growth." (PMID 40581884, 2025). "CAFs promote tumor invasion and metastasis by promoting the release of FGF2 by secreting insulin-like growth factor-binding protein 7 (IGFBP7), which in turn affects the polarization of TAMs towards the M2 type and their infiltration into tumor tissue." (PMID 40038745, 2025). "Our results suggest that low compressive forces in the tumor microenvironment induce local immunosuppression via FGF2 secretion arising from phenotypic plasticity of tumor cells." (PMID 40425576, 2025). "For instance, in the AURELIA study involving platinum-resistant patients, tumor tissue demonstrated a 3.2-fold increase in FGF2 mRNA expression, while the combination of FGFR inhibitors raised the ORR to 27%." (PMID 40474872, 2025). "The resulting nanocomposites reduced the tumor volume by inhibiting cell proliferation that was accompanied by inhibition of FGF2 (fibroblast growth factor-2) and downregulation of VEGF expression." (PMID 40429669, 2025). "PDGF‐C‐induced FGF2 activates ECs, fostering tumour growth and invasion while linking different types of tumour parenchyma and stroma." (PMID 40268524, 2025). "Specifically, IGFBP7 has been shown to augment tumor-associated macrophage (TAM) infiltration, thereby promoting GC advancement, through the activation of the FGF2/FGFR1/PI3K/AKT signaling axis." (PMID 40485724, 2025). "The binding of E2F3 to the promoter of FGF2, confirmed by ChIP-qPCR, increases FGF2 expression, thereby promoting tumor proliferation and metastasis by activating FGFR1, PI3K/Akt, and MEK/ERK signaling pathways in HCC cells." (PMID 40211368, 2025). "It was shown that the Adora2b, inhibitor PSB1115 reduced the number of CAFs expressing fibroblast activating protein (FAP) and fibroblast growth factor (FGF-2) in the tumor microenvironment of melanoma mice." (PMID 41346607, 2025). "Core genes with a higher DC (> 8), EC (> 0.06), LAC (> 2.0), BC(> 200), and NC(> 0.3) in the enriched modules were also expressed differentially in TCGA‐CHOL data (36 tumor samples and 9 adjacent cancer samples), including FGF2, IGF1, CAV1, SPON1, and ADAMTS4." (PMID 40304434, 2025). "Elevated FGF-2 levels have been shown to enhance tumor cell proliferation, angiogenesis, and migration, contributing to increased metastatic potential." (PMID 39946200, 2025). "It serves as a scaffold for tumor-associated growth factors, including vascular endothelial growth factor(VEGF) and fibroblast growth factor-2(FGF-2)." (PMID 41244895, 2025). "The investigation has shown that tumor tissues and tumor-associated macrophages (TAMs) exhibit higher quantities of MALAT-1 and fibroblast growth factor 2 (FGF-2) than normal tissue." (PMID 38511067, 2024). "As an outcome of this interaction, VEGF-B effectively inhibited FGF2-driven angiogenesis and tumor growth." (PMID 39272961, 2024). "In vivo dynamic imaging showed the rapid and continuous accumulation of radiolabeled FGF-2 in the tumor within 90 min from i.v. injection." (PMID 38672507, 2024). "H2O2, in this context, enhances the activation of the Fibroblast-FGF2 system, thereby exerting suppressive effects on the tumor microenvironment." (PMID 37469162, 2024). "For example, T cell‐derived interferon γ (IFNγ) can promote tumor FGF2 signal transduction, reduce nicotinamide adenine dinucleotide (NAD+), activate β‐catenin acetylation, and reprogram tumor dormancy." (PMID 38318160, 2024).